ARHGEF18 (Rho/Rac guanine nucleotide exchange factor 18)
Description:
Acts as a guanine nucleotide exchange factor (GEF) for RhoA GTPases. Its activation induces formation of actin stress fibers. Also acts as a GEF for RAC1, inducing production of reactive oxygen species (ROS). Does not act as a GEF for CDC42. The G protein beta-gamma (Gbetagamma) subunits of heterotrimeric G proteins act as activators, explaining the integrated effects of LPA and other G protein-coupled receptor agonists on actin stress fiber formation, cell shape change and ROS production. Required for EPB41L4B-mediated regulation of the circumferential actomyosin belt in epithelial cells.
Synonyms: p114RhoGEF; SA-RhoGEF; KIAA0521; P114-RhoGEF; MGC15913; RP78
Tractability: Antibody: UniProt places it where antibodies can reach, with high confidence; its Gene Ontology location is reachable by antibodies, with high confidence; the Human Protein Atlas places it where antibodies can reach. PROTAC: ubiquitination databases record sites on it; its protein half-life has been measured.
Gene: Protein-coding gene on chromosome 19 (7,348,937 to 7,472,485, forward strand). Ensembl gene ENSG00000104880.
Subcellular location: Cytoplasm; Cytoplasm, cytoskeleton; Cell membrane; Apical cell membrane
Subcellular location (Human Protein Atlas): Cytosol; Plasma membrane
Pathways (Reactome):
Signal Transduction: G alpha (12/13) signalling events; NRAGE signals death through JNK; RAC1 GTPase cycle; RHOA GTPase cycle; TGF-beta receptor signaling in EMT (epithelial to mesenchymal transition)
Gene Ontology:
Molecular function: guanyl-nucleotide exchange factor activity; protein binding
Biological process: actin cytoskeleton organization; negative regulation of stress fiber assembly; protein localization to cell-cell junction; regulation of cell shape; small GTPase-mediated signal transduction; regulation of Rho protein signal transduction
Cellular component: apical part of cell; apical plasma membrane; cytosol; extracellular exosome; plasma membrane; cell junction; cytoplasm; cytoskeleton
Genetic constraint (gnomAD): Loss-of-function variants: 88 observed, 129.6 expected, observed/expected ratio (o/e) 0.68, 90% interval 0.57 to 0.81. The upper end of that interval is the gene's LOEUF score, 0.81, which puts it in group 3 of 6, group 1 being the genes least tolerant of losing a copy. Missense variants: 1,584 observed, 1,676.9 expected, observed/expected ratio (o/e) 0.94, 90% interval 0.91 to 0.99. Synonymous variants: 740 observed, 686.11 expected, observed/expected ratio (o/e) 1.08, 90% interval 1.01 to 1.15.
Gene-disease validity (ClinGen):
ClinGen rates the evidence that ARHGEF18 causes each of these diseases.
inherited retinal dystrophy (autosomal recessive): Moderate. An instance of retinal degeneration that is caused by an inherited modification of the individual's genome.
Homologues: Orthologues: macaque ARHGEF18 (95% identical), dog ARHGEF18 (76% identical), mouse Arhgef18 (75% identical), pig ARHGEF18 (75% identical), rat Arhgef18 (75% identical), chimpanzee ARHGEF18 (74% identical), tropical clawed frog arhgef18 (48% identical), zebrafish arhgef18b (39% identical), zebrafish arhgef18a (29% identical), Drosophila melanogaster cyst (19% identical), Caenorhabditis elegans prhg-1 (8% identical). Paralogues in human: ARHGEF28 (32% identical), ARHGEF2 (23% identical), ARHGEF12 (14% identical), ARHGEF11 (14% identical), ARHGEF1 (12% identical), PLEKHG6 (10% identical), NET1 (7% identical), ARHGEF3 (7% identical).
Diseases named in the same sentence as ARHGEF18 in open-access papers:
ARHGEF18 is named in the same sentence as 20 diseases in open-access papers, as found by Europe PMC text mining. Sharing a sentence is not in itself a finding about the gene and the disease. The quoted sentences say what the papers report.
pulmonary arterial hypertension (2 papers, 2018 to 2025). Pulmonary arterial hypertension (PAH) is a group of diseases characterized by mean pulmonary artery pressure >20 mmHg and elevated pulmonary arterial resistance leading to right heart failure. "In summary, it is biologically plausible that the rs3745357 variant in ARHGEF18 may have an effect on individual susceptibility to pulmonary hypertension." (PMID 30405854, 2018). "ARHGEF18 has been identified as upregulated in the lung tissues of rat models of pulmonary artery hypertension introduced by hypoxia or monocrotaline (MCT)." (PMID 30405854, 2018). "Clinical studies have reported that mutations in ARHGEF18 lead to increased susceptibility to nonidiopathic pulmonary hypertension associated with coronary artery disease, and systematic knockdown of Arhgef18 results in embryonic death in mice." (PMID 40159883, 2025). "In the present study, we aimed to investigate the association between ARHGEF18 rs3745357 polymorphism and nonidiopathic pulmonary arterial hypertension susceptibility (niPAH)." (PMID 30405854, 2018).
cardiomyopathy (1 paper, 2025). A disease of the heart muscle or myocardium proper. "Our study results suggest that Arhgef18 cKO mice could provide an ideal animal model for the genetic investigation of cardiomyopathy." (PMID 40159883, 2025).
cleft lip (1 paper, 2025). Congenital defect in the upper lip where the maxillary prominence fails to merge with the merged medial nasal prominences. "After clumping, we identified 18 regions (2 mapping to ARHGEF18 (19p13.2) and ARHGEF19 (1p36.13) were novel) which showed the smallest p-values in the cleft lip with or without cleft palate (CL/P) or nsCL/P subtype GWAS and which were associated with both CLO and CLP." (PMID 41075272, 2025).
cone dystrophy (1 paper, 2024). An inherited ocular disorder characterized by the loss of cone cells, the photoreceptors responsible for both central and color vision. "Patient one had a clinical diagnosis of cone dystrophy, and the Invitae kit reported VUS in ARHGEF18, INPP5E, NPHP3, and SEMA4A; BG reported VUS in ARHGEF18 and SEMA4A." (PMID 38892829, 2024).
cyst (1 paper, 2022). A sac-like closed membranous structure that may be empty or contain fluid or amorphous material. "Because ARHGEF18 contributes to the maintenance of epithelial morphogenesis, such as 3D cyst formation observed in Caco-2 cells, we next assessed cyst formation." (PMID 36404918, 2022).
squamous cell lung carcinoma (1 paper, 2018). A carcinoma arising from squamous bronchial epithelial cells. "Abnormal ARHGEF18 expression levels and DNA variants in the gene have been associated with different diseases, including adult-onset retinal degeneration, systemic capillary leak syndrome, and squamous-cell lung carcinoma." (PMID 30405854, 2018). "The abnormal ARHGEF18 expression level and DNA variants in the gene have been associated with different diseases, including adult-onset retinal degeneration, systemic capillary leak syndrome, and squamous-cell lung carcinoma." (PMID 30405854, 2018).
tumor (2 papers, 2015 to 2022). "For instance, mutations in the IGDCC4, ARHGEF18, MAP2K3 or AIF1L genes, which were observed in fractions exceeding 80% in the primary tumor ranged from 0 to 86% in the PDXs or secondary nodules." (PMID 26334103, 2015). "The ARHGEF18 (Rho/Rac Guanine Nucleotide Exchange Factor 18), also known as P114-RhoGEF, activates the downstream gene RhoA, which is important for cell migration and tumor progression." (PMID 36552904, 2022).
lip (1 paper, 2025). "Novel loci include those mapping to LHX8 and TSBP1 (combined clefts), ARHGEF18 and ARHGEF19 (cleft lip with/without palate), FBN2 (cleft lip only), SLC35B3 (cleft palate only), CASC20 (Pierre Robin Sequence) and CHRM2 (non-syndromic cleft palate only)." (PMID 41075272, 2025).
ARHGEF18 also shares sentences with these, for which no sentence is quoted: pulmonary hypertension (2 papers); Sepsis (2); adenocarcinoma (1); cancer (1); cleft palate (1); coronary artery disease (1); lung carcinoma (1); melanoma (1); optic atrophy (1); retinopathies (1); squamous cell carcinoma (1); Systemic capillary leak syndrome (1).